TNF (tumor necrosis factor)
Diseases named in the same sentence as TNF in open-access papers (continued):
Sharing a sentence is not in itself a finding about the gene and the disease.
preeclampsia (continued). "The factors released include pro-inflammatory cytokines such as hsCRP and TNF-α, which have been reported to be elevated in mothers with preeclampsia." (PMID 36420416, 2022). "In order to determine if PDMSCs-CM treatment was effective also at the placental level, we evaluated placental expression of sFlt-1, TNF-α, and IL-6, key hallmarks of preeclampsia, in CM and control mice." (PMID 35163594, 2022). "ASA administration results in the downregulation of the transcription of the pro-inflammatory cytokines TNFα, IFN-γ, IL1, IL6, and IL8, whose genes are regulated by NFĸB; all of these cytokines are strongly linked with the pathomechanism of preeclampsia." (PMID 35270023, 2022). "At the same time, the upregulation of the proinflammatory cytokines IL-1β and TNF-α in the serum of preeclampsia patients suggested the activation of systemic inflammation in preeclampsia patients." (PMID 36310595, 2022). "Increased platelet thromboxane synthesis only occurs in severe preeclampsia cases, and proinflammatory cytokines such as IL-6 and tumor necrosis factor alpha (TNF-α) are secreted excessively by maternal immune cells." (PMID 35888713, 2022). "The plasma level of proinflammatory cytokine tumor necrosis factor-α (TNFα) was significantly higher in preeclampsia participants." (PMID 35455936, 2022). "Compared with healthy group, the levels of serum Lp-PLA2, CRP, IL-6 and TNF-α in gestational hypertension group, mild preeclampsia group and severe preeclampsia group all increased." (PMID 35784937, 2022). "The results are contradictory, with most studies reporting an increase of this marker in preeclampsia, including the present study in which meta-analysis showed a significant difference in TNF-α levels compared to control." (PMID 36034841, 2022). "Analysis of TNF-alpha, an important inflammatory marker, showed higher levels in women with preeclampsia (p < 0.03) compared to controls." (PMID 36034841, 2022). "There have been considerable studies to support that the level of TNF can be used as a biomarker for preeclampsia diagnosis." (PMID 36686428, 2022). "In the third trimester, several studies report significantly higher maternal serum TNF-α concentrations in women with preeclampsia compared to controls while others have detected similar or nonsignificantly different concentrations." (PMID 33680514, 2021). "We show that cytokines TNF-α, IL-6, and IL-35 are elevated, and IL-10 is reduced in the sera of preterm preeclampsia cohort as compared to control preterm cohort, suggesting a role of chronic inflammation in disease pathology." (PMID 34195300, 2021). "Overall, most work indicates that TNF-α concentrations are higher in preeclampsia compared to healthy pregnant women, reflecting the enhanced proinflammatory systemic environment." (PMID 33680514, 2021). "Further evidence supporting the involvement of TNFα in uterine vascular dysfunction in preeclampsia comes from animal studies." (PMID 34445328, 2021). "Inflammatory markers (IL-6, IL-8 and TNF-alpha) were increased in the CSF of women with eclampsia, compared to those with preeclampsia and women with normotensive pregnancies." (PMID 34831266, 2021). "Women with eclampsia (n = 4) showed increased CSF concentrations of all pro-inflammatory cytokines and TNF-alpha compared to women with normotensive pregnancies (n = 7) and also for interleukin-6 and TNF-alpha compared to women with preeclampsia (n = 4)." (PMID 34831266, 2021). "TNF-α, which is upregulated in preeclampsia, is the strongest stimulator of CX3CL1 synthesis in placenta." (PMID 33496844, 2021). "We prospectively examined a cohort of maternal-infant dyads with preeclampsia for maternal inflammatory cytokines at time of preeclampsia diagnosis and delivery, and fetal cord blood cytokines (IL-1β, IL-6, IL-8, and TNF-α)." (PMID 34780565, 2021). "Dramatic upregulation of TNF‐α, IL‐6, and IL‐1β was observed in placental tissues from preeclampsia patients compared to healthy donors." (PMID 34089575, 2021).
preeclampsia (continued). "TNF-α is increased in plasma of women with preeclampsia as compared to normal pregnant women, which increases vascular permeability and lymphocyte activation and disrupts mitochondrial function leading to oxidative stress." (PMID 34681861, 2021). "Decreased levels of anti-inflammatory cytokines (IL-10, IL-4) and increased pro-inflammatory cytokines (TNF-α, IL-6) in the circulation and placental tissue support the inflammatory background of preeclampsia." (PMID 35004644, 2021). "A number of factors found in preeclampsia, such as the inflammatory cytokines IL-6 and TNFα, disrupt placental function, resulting in the production of toxic EVs." (PMID 34440672, 2021). "Plasma levels of interleukin-6 (IL-6) and tumor necrosis factor-α (TNF-α) have been shown to be elevated in preeclampsia." (PMID 34045549, 2021). "In the present study, we found increases in TNF-α and miR-31/155 levels and reduced numbers of circulating EPCs in patients with preeclampsia." (PMID 32770080, 2020). "Plasma levels of both miRNAs and TNF-α were found to be increased in patients with preeclampsia and rheumatoid arthritis and were inversely correlated with eNOS expression in patient-derived endothelial cells." (PMID 32770080, 2020). "The umbilical serum level of inflammatory markers (interleukin-6, interleukin-8, and tumor necrosis factor-alpha) in pregnancies complicated by preeclampsia was significantly increased compared with normal pregnancies." (PMID 32587622, 2020). "Pramatirta found increased expression of TNF-α and caspase-3, and apoptotic index in preeclampsia serum-induced trophoblast cells compared to that of normal and controls." (PMID 32216842, 2020). "For instance, the serum uric acid levels rise as TNF-alpha-producing monocytes also increase in women with preeclampsia." (PMID 32283759, 2020). "Inflammatory cytokines, TNF-α, IL-6, and IL-8, are significantly increased in preeclampsia, and IL-10 is significantly decreased compared to normal pregnancy, therefore promoting the M1 phenotype." (PMID 33013837, 2020). "For example, circulating TNF levels have been shown to be increased in women with preeclampsia; reviewed in7." (PMID 31266978, 2019). "Staining of the subcutaneous adipose tissue sections revealed a greater inflammatory response in preeclampsia, based on the higher levels of both TNF-alpha and MCP-1 compared to normotensive pregnancies (p < 0.001 and 0.024, respectively)." (PMID 31521202, 2019). "This is in agreement with recent studies of maternal inflammation (cytokines such as IL-6, TNF-α) in preeclampsia, whereby low level inflammation is evident early in pregnancies but is amplified in the third trimester of pregnancy." (PMID 30976066, 2019). "This is plausible since preeclampsia patients have increased circulating levels of tumor necrosis factor alpha (TNFα), interleukin (IL)-2, IL-6, and IL-17." (PMID 31434191, 2019). "Meta-analyses have described a potential association between preeclampsia and elevated levels of serum triglycerides, cholesterol, and inflammatory markers including CRP, IL-6, IL-8, and TNFα, some of which precede the onset of preeclampsia." (PMID 31590294, 2019). "We have confirmed that this is also likely in preeclampsia in our functional experiments, demonstrating that placental factors or TNFα significantly reduced endothelial GATA2 coincident with increased VCAM-1 expression." (PMID 30659233, 2019). "Not only the baseline release of pro-inflammatory cytokines from peripheral blood monocytes was increased in preeclampsia, LPS-induced TNF-α, IL-1β, and IL-6 release was also enhanced in women with preeclampsia." (PMID 31138166, 2019). "In a very interesting study by Azizieh and Raghubaty, elevated TNF-α serum levels were correlated with severe pregnancy complications, e.g., recurrent miscarriages, premature rupture of membranes, preeclampsia, and intrauterine growth restriction." (PMID 30518097, 2018).
preeclampsia (continued). "Seven alleles were significantly or marginally significantly associated with preeclampsia, which involved six genes (rs4762 in AGT, rs1800896 in IL-10, rs1800629 and rs1799724 in TNFα, rs2070744 in NOS3, rs7412 in APOE, and rs2549782 in ERAP2)." (PMID 30112393, 2018). "Elevations in circulating leptin are associated to increased circulating levels of TNF-α in obese pregnant rats, and we have shown that women with preeclampsia have increased levels of TNF-α, IL-6 and C-reactive protein (CRP)." (PMID 30618843, 2018). "The pro-inflammatory cytokine TNFα is also believed to contribute to the increased BBB permeability in preeclampsia." (PMID 30459636, 2018). "Tumor necrosis factor-α also inhibits the production of NO and thus influences the circulating levels of angiogenic factors in the second stage of preeclampsia." (PMID 30079067, 2018). "Studies have, however, reported highly variable results of the circulating levels of TNF-α in preeclampsia, with some showing increased, unchanged, or even insignificantly decreased levels, possibly due to differences in timing and study method used." (PMID 30079067, 2018). "During preeclampsia,increased levels of tumor necrosis factor (TNF)-α and interleukin (IL)-6 are presentin the circulation and in the trophoblast cells of the placenta, whereas the contentof IL-10 and IL-4 is decreased." (PMID 29898033, 2018). "Future study is warranted to investigate the molecular mechanism of VD action on downregulating TNF-α and upregulating IL-10 during preeclampsia." (PMID 29225576, 2017). "In a rat model of preeclampsia, VD supplementation restores angiogenic balance and decreases tumor necrosis factor-α (TNF-α), and importantly, reduced blood pressure." (PMID 29225576, 2017). "Preeclampsia is characterised by significantly higher levels of pro-inflammatory cytokines such as IL-6 and TNF-α, when compared with normal pregnant women." (PMID 28103790, 2017). "In humans, preeclampsia and placental ischemia, which are associated with increased incidence of ASD, also increase TNF-α concentrations and this in turn can alter the permeability of the blood-brain barrier and influence brain development and function." (PMID 29137272, 2017). "We also reported a significant increase in endothelial TLR-9 gene expression with a consequent increase in pro-inflammatory cytokine TNF-α gene expression respectively in HUVEC treated with preeclampsia plasma." (PMID 27604418, 2016). "In preeclampsia, the pro-inflammatory TNF-α and IL-6 and C-reactive protein are higher compared to normal pregnancy." (PMID 26247971, 2015). "The ratios IL-2/IL-10 and TNF-α/IL-10 in maternal serum are higher in preeclampsia than in normal pregnancy." (PMID 26247971, 2015). "In particular, IL-6 and TNF-α are important players contributing to the endothelial dysfunction observed in preeclampsia." (PMID 26247971, 2015). "The biochemical data from this study relating to the inflammatory mediators TNF-α and IL-1β and the preeclampsia biomarkers sFlt-1 and PlGF are also worthy of note." (PMID 24586695, 2014). "Elevated TNF-α levels have been described in both the maternal circulation and amniotic fluid of preeclampsia patients as well as in the placenta and circulation of rodents undergoing placental ischemia." (PMID 25249978, 2014). "TNF-α is a pleiotropic cytokine that has been found to be involved in many activities in preeclampsia." (PMID 25302305, 2014). "In asymptomatic patients (patients who later developed preeclampsia in the second trimester), the level of TNF-α in the first trimester was 2-fold higher compared to healthy controls." (PMID 25302305, 2014). "The cytokines TNF-α and IL-1β are primarily produced by macrophages and in preeclampsia participate in abnormal extravillous trophoblast invasion." (PMID 24586695, 2014).
preeclampsia (continued). "In early onset of preeclampsia, findings on TNF-α and interleukin-2 (an anti-inflammatory cytokine) suggested that there is an imbalance of proinflammatory and anti-inflammatory cytokines ratio." (PMID 25302305, 2014). "TNF-α overproduction has been observed in patients with preeclampsia and in animal models of preeclampsia, which suggests that it plays an important role in maternal physiological response observed in preeclampsia." (PMID 24659862, 2014). "On the other hand, other authors have demonstrated that level of TNF-α increased significantly in women diagnosed with preeclampsia compared with healthy control." (PMID 25302305, 2014). "Toll-like receptor which is the main danger signalling pathway involved in the pathophysiology of preeclampsia increases the production of TNF-α." (PMID 25302305, 2014). "Other models for preeclampsia, TNF infusion or IL-6 infusion in pregnant Sprague-Dawley rats did show decreased total vascular reactivity in the aorta as compared with control rats." (PMID 24223202, 2013). "As pregnancy develops, high TNF-α concentrations have been related to the development of preeclampsia and gestational diabetes mellitus (GDM), reduced IL-10 levels, and preterm birth." (PMID 22462002, 2012). "TNF-alpha is produced by monocytes, induces apoptosis, and inhibits proliferation of trophoblast cells in preeclampsia." (PMID 21253506, 2010). "Maternal serum levels of IL-6 and TNF-alpha play a significant role in pathogenesis of preeclampsia." (PMID 21253506, 2010). "On the contrary, a statistically significant difference was found in TNF-alpha levels in women with preeclampsia compared to normal pregnant women (0.80 pg/ml range: 0.67–0.92 pg/ml versus 0.60 pg/ml range: 0.49–3.01 pg/ml, P : .04)." (PMID 21253506, 2010). "An interesting finding of this study is that elevated circulating TNF-alpha and IL-6 levels were detected long after delivery in women with preeclampsia." (PMID 21253506, 2010). "In the present study, we have evaluated maternal TNF-alpha and IL-6 plasma levels in normotensive pregnant women as well as in women with preeclampsia." (PMID 21253506, 2010). "On the contrary, others did not manage to identify a correlation between maternal serum levels of IL-6 or TNF-alpha and preeclampsia." (PMID 21253506, 2010). "Several investigators have reported that serum concentrations of TNF-α were significantly higher in the first and second trimester among pregnant women who subsequently developed preeclampsia compared to those in the control group." (PMID 16259641, 2005). "Increased amniotic fluid concentrations of TNF-α in patients with severe preeclampsia suggest a role for this cytokine in the pathophysiology of this disease." (PMID 16259641, 2005). "TNF-α is another pro-inflammatory cytokine that its contribution in the pathogenesis of preeclampsia has been suggested in recent studies." (PMID 16259641, 2005). "IL-6, CRP and TNF-α in females with preeclampsia were elevated in comparison to the controls." (PMID 41394354, 2025). "NF-κB–responsive miR-31-5p led by TNF- α decrease eNOS expression in preeclampsia." (PMID 38267979, 2024). "Hence, in obese women with preeclampsia, the concentration of adiponectin decreases, and the concentrations of TNF-α, CRP, and IL-6 plasma increase." (PMID 37964253, 2023). "The pregnant Dahl salt sensitive (Dahl-SS/Jr) rat has been described as a model of spontaneous superimposed preeclampsia as it displays clinical features of preeclampsia including hypertension, proteinuria, placental hypoxia, increased sFlt-1 and TNF-alpha, and fetal growth restriction." (PMID 37064920, 2023). "Expression levels of chemerin, IL-6, and TNF-α are increased in gestational diabetes, and the increases in chemerin in late pregnancy positively correlate with the ratio of sFlt-1 to PlGF as a marker of preeclampsia." (PMID 37964253, 2023).
preeclampsia (continued). "Regarding changes in the cytokine profile in preeclampsia, there is evidence that the levels of pro-inflammatory cytokines, namely TNF-α and IL-6, are increased in preeclampsia, while the concentrations of anti-inflammatory cytokines, namely IL-4 and IL-10, are decreased." (PMID 37168313, 2023). "They determined whether hypoxia/oxidative stress, an underlying pathophysiology of preeclampsia, would modulate ADAM17 expression and subsequently induce TNF-α production in placental trophoblasts." (PMID 37374349, 2023). "Within the context of pregnancy, in in vitro trophoblast experiments, TNF-α and Gal-3 have been shown to regulate each other, likely by a positive feedback mechanism, and may contribute to inflammatory processes in preeclampsia." (PMID 36652019, 2023). "In Pinheiro article also non-association between TNF-α (− 308 G → A), IL-6 (− 174 G → C), or IL-10 (− 1082 G → A) polymorphisms and preeclampsia was reported." (PMID 38057745, 2023). "Interestingly, hydroxychloroquine had previously been shown to rescue tight junction loss in human umbilical vein derived endothelial cells (HUVECs), mediated by tumour necrosis factor-α (TNFα) and preeclampsia sera treatments, in vitro." (PMID 36417467, 2022). "In addition, preeclampsia inhibited TNF-α-induced migration of HUVEC of female offspring, with an opposite effect on HUVEC of male offspring." (PMID 36420416, 2022). "We concluded that some inflammatory markers in our meta-analysis such as leptin, total cholesterol, triglycerides, TNFα and C-reactive protein were increased in pregnant women with preeclampsia compared to pregnant control women, so inflammatory markers are important markers of preeclampsia." (PMID 36034841, 2022). "Furthermore, hydroxychloroquine was shown to rescue tight junction loss in human umbilical vein derived endothelial cells (HUVECs), mediated by tumour necrosis factor-α (TNFα) and preeclampsia sera treatments, in vitro." (PMID 36417467, 2022). "However, the relationship between the disorder of TNF-α and adverse pregnancy outcomes, including preeclampsia (PE), intrauterine growth restriction (IUGR), spontaneous abortion (SA), preterm birth and so on, is still indefinite." (PMID 35687009, 2022). "Likewise, two other systematic reviews also identified elevated levels of TNF-α, IL-6, and IL-10 in studies on preeclampsia." (PMID 36034841, 2022). "In preeclampsia, an exaggerated immune activation mediated through cytokines released from placental tissue precipitates macrophage deposition in the placenta leading to TNF-α-induced apoptosis of trophoblasts." (PMID 36421613, 2022). "Therefore, we evaluated the effects of PDMSCs-CM administration on maternal blood pressure, proteinuria, fetal outcome, and placental expression of sFlt-1, TNF-α, and IL-6 in an LPS-induced mouse model of preeclampsia." (PMID 35163594, 2022). "Given inflammation and placental hypoxia play crucial role in pathophysiology of preeclampsia, we examined the effect of pro-inflammatory cytokines (IL-6 and TNFα) and hypoxia on LGALS3 and LGALS3BP mRNA expression in placental cytotrophoblast and syncytiotrophoblast cells." (PMID 36311252, 2022). "In preeclampsia, the production/release of TNFα in the placenta is increased." (PMID 34445328, 2021). "TNF-α has been shown to be high in SGA associated with preeclampsia, but not with idiopathic SGA, and in intrauterine growth retardation (IUGR) associated with placental insufficiency but not in those with IUGR with normal placental perfusion." (PMID 33898918, 2021). "Correspondingly, circulating TNFα level increases in women with preeclampsia." (PMID 34445328, 2021). "In maternal vessels, an increase in pro-inflammatory TNFα and IL6 contributes to causing endothelial dysfunction, which is a hallmark of preeclampsia mainly characterized by reduced production of vasodilation factors and an increase in the permeability of endothelial cells." (PMID 32116801, 2020).